ALB (albumin)
Diseases named in the same sentence as ALB in open-access papers (continued):
Sharing a sentence is not in itself a finding about the gene and the disease.
Anorexia (continued). "Independent predictors of SFTS in patients with suspected scrub typhus are low albumin level at admission and anorexia." (PMID 27767909, 2016). "Inflammation reduces albumin concentration through cytokine production, reduces protein intake, and increases endogenous albumin catabolism by inducing anorexia." (PMID 27127544, 2016). "Less commonly, increased serum ALT and GLDH activity, aggression, anorexia, emaciation and decreased T4 and serum albumin were reported." (PMID 27206489, 2016). "Additionally, inflammation can suppress the synthesis of ALB, and the anorexia induced by inflammation diminishes ALB intake." (PMID 40271132, 2025). "We observed that the variables lethargy, anorexia, albumin, and sodium were predictors of HA." (PMID 39764376, 2024). "The multivariate logistic regression model conducted in this study identified a significantly increased likelihood of a HA diagnosis in the presence of lethargy, anorexia and low levels of sodium and albumin, with that possibility increasing with lower values for these parameters." (PMID 39764376, 2024). "He developed anorexia, a decrease in albumin, as well as hemoglobin." (PMID 37631384, 2023). "By contrast, in humans, serum albumin concentrations peak at around 20 years and gradually decrease with age, potentially due to liver degeneration, as that is the primary site of albumin production, or to protein intake reduction, known as geriatric anorexia." (PMID 37795017, 2023). "All dogs had resolution of anorexia, three had stable or improved serum albumin concentrations, four had improved or normalized serum globulin concentrations, and four dogs had improved or normalized serum cholesterol concentrations 2–3 days after initiating the diet." (PMID 35739930, 2022). "In laboratory findings, the mean albumin levels were significantly lower in the anorexia group." (PMID 34071957, 2021). "Low preoperative prealbumin, albumin, total lymphocyte count, BMI, and anorexia have been demonstrated to be independent predictors of postoperative complications, and these factors may be useful in elucidating patients who will benefit the most from perioperative nutritional optimization." (PMID 39617150, 2025). "Albumin levels and to a lesser extent apolipoproteins, trended lower in turtles presenting with trauma than those categorized as intestinal floaters that may correspond with the severity of tissue injury or length of anorexia." (PMID 33959286, 2021). "The results indicated that BMI, body weight, abdominal circumference, albumin, prealbumin, MNA-SF scale score, simple anorexia scale score, and simple appetite scale score were significantly lower in the malnourished group compared to the non-malnourished group (P < 0.01)." (PMID 40813643, 2025). "Regarding nutritional parameters, mean weight and serum albumin concentrations remained consistent throughout the study duration, suggesting that diarrhea did not lead to poor nutritional status or anorexia." (PMID 37910313, 2024). "Tachycardia, cough, fever at presentation and duration, anorexia, and higher ALT, hematocrit, urea, and albumin levels were indicative of DF, while higher platelet count, hemoglobin, lymphocyte proportion, creatinine, bilirubin, and more myalgia/arthralgia were predictive of chikungunya." (PMID 23029573, 2012). "In addition, although there are no reports of a correlation between albumin and motilin concentrations, when anorexia is accompanied by hunger, motilin is overproduced, which also leads to nausea." (PMID 40045433, 2025). "In addition, malnourished patients had significantly more often low albumin concentrations than non-malnourished, and frail patients had significantly more often low hemoglobin values and more often anorexia than non-frail patients." (PMID 31029082, 2019). "Moreover, short-term vomiting or anorexia did not lead to a decrease in serum ALB." (PMID 33329359, 2020).
esophageal cancer (82 papers, 2010 to 2026). A primary or metastatic malignant neoplasm involving the esophagus. "Severely deficient serum albumin after MIE was an indicator of AL in esophageal cancer patients treated with NCT." (PMID 38066484, 2023). "A retrospective study in esophageal cancer has demonstrated that a better serum albumin-based nutritional condition is significantly associated with the CD8-positive cell count." (PMID 33635904, 2021). "Pre-operative variables including weight loss, low serum albumin and pre-albumin, Geansler’s index, all have strong predictive relation to mortality on patients who undergo esophagectomy for esophageal cancer." (PMID 20871187, 2010). "Measurement values of albumin, condition of “inguinal hernia,” and procedure of “CT of thyroid with contrast” were negatively associated with prolonged postoperative stay, while condition of “malignant tumor of esophagus” and procedure of “plain film of head” were positively associated." (PMID 37955965, 2023). "By screening the titles and abstracts, 47 studies comparing albumin-bound paclitaxel with paclitaxel for esophageal cancer were included." (PMID 40900779, 2025). "This study systematically evaluates the efficacy and safety of albumin-bound paclitaxel and paclitaxel in esophageal cancer treatment using evidence-based medicine, aiming to provide a basis for clinical decision-making." (PMID 40900779, 2025). "There is a clear distinction between the use of albumin-bound paclitaxel and paclitaxel in the chemotherapy regimen of “Esophageal Cancer Diagnosis and Treatment Guidelines 2024” by the Chinese Society of Clinical Oncology (CSCO)." (PMID 40900779, 2025). "The Glasgow Prognostic Score (GPS), the modified GPS, and the serum C-reactive protein to albumin ratio (CAR) are prognostic markers in patients with esophageal cancer treated by chemotherapy, CRT, and radiotherapy." (PMID 40155587, 2025). "This approach aims to increase hemoglobin and albumin levels to address malnutrition, thereby enhancing the prognosis for patients with esophageal cancer." (PMID 39301556, 2024). "A study found that a lower level of albumin was an independent predictor of early death (less than 6 months) in esophageal cancer." (PMID 36959779, 2023). "Overall, nab-paclitaxel and albumin-based paclitaxel formulations offer promising prospects for the treatment of esophageal cancer, with improved therapeutic efficacy and reduced adverse effects." (PMID 37520291, 2023). "Previously, a certain value of serum albumin (e.g. 35 g/L) was identified as a cutoff for predicting AL after surgery in esophageal cancer patients." (PMID 38066484, 2023). "In patients with esophageal cancer, high albumin levels have higher total protein levels and a higher quality of life than those with low albumin levels." (PMID 35495765, 2022). "Patients with esophageal cancer receiving CCRT who exhibited increased albumin levels during the treatment course had better survival outcomes." (PMID 35804884, 2022). "The C-reactive protein–ALB ratio before treatment can be used as a potential prognostic biomarker in patients with head and neck cancer, esophageal cancer, and bile duct cancer; an elevated C-reactive protein–ALB ratio predicts a poorer prognosis." (PMID 36428725, 2022). "Excessively low prognostic nutritional index (PNI) based on serum ALB level and LYM count is an independent risk factor of affecting the overall survival rate of esophageal cancer patients." (PMID 34222299, 2021). "The average pre-albumin in esophagus cancer patients was 22.0 mg/dL in Saudi Arabia, and 21.7 mg/dL in China." (PMID 33800823, 2021). "Albumin has been reported as an independent predictive factor of complete response to CRT in esophageal cancer patients." (PMID 32856860, 2020). "The Glasgow Prognostic Score, which uses CRP and albumin, is one such example validated for colorectal and esophageal cancer." (PMID 33054830, 2020).
esophageal cancer (continued). "Serum PD‐L1 levels were positively correlated with neutrophil counts and CRP and SCC‐Ag levels and negatively correlated with albumin levels in patients with surgically treated esophageal cancer in this study." (PMID 31865635, 2020). "NLR/Alb (neutrophil lymphocyte ratio/albumin ratio), is a prognostic index for esophageal cancer has been confirmed." (PMID 30762804, 2019). "In recent years, the role of pre-treatment C-reactive protein/albumin ratio (CAR) in prognosis of esophageal cancer (EC) has been investigated by several studies." (PMID 31783812, 2019). "Another study from France found that pretreatment serum albumin level > 35 g/l was the only independent predictive factor of complete response to chemoradiotherapy (CRT) in esophageal cancer patients." (PMID 30116261, 2018). "Recently, studies have shown that plasma D-dimer and serum albumin are prognostic markers for esophageal cancer." (PMID 26754834, 2016). "The following search terms were used: ("esophageal cancer" OR "esophageal carcinoma" OR "esophageal neoplasm" OR "oesophageal cancer") AND ("C-reactive protein-albumin-lymphocyte" OR "CALLY" OR "CRP-albumin-lymphocyte") AND ("survival" OR "prognosis" OR "mortality" OR "outcome")." (PMID 41179090, 2025). "Camrelizumab plus albumin paclitaxel and carboplatin were found to be safe and effective in the neoadjuvant treatment of borderline resectable or unresectable locally advanced esophageal cancer." (PMID 38316630, 2024). "A retrospective analysis was conducted on 27 patients with borderline resectable or unresectable locally advanced esophageal cancer who received neoadjuvant treatment with camrelizumab plus albumin paclitaxel and carboplatin at Shanxi Cancer Hospital from January 2020 to March 2022." (PMID 38316630, 2024). "However, as a disease highly related to the dietary habits, chronic malnutrition with a low value of serum albumin can be observed in some of esophageal cancer patients, even before diagnosis." (PMID 38066484, 2023). "Conservative fluid management and liberal use of diuretics or albumin might be warranted for those undergoing surgery for esophageal cancer with a history of c-AKI." (PMID 36973771, 2023). "Therefore, further study in wider populations is warranted to validate the efficacy of perioperative decreased serum albumin levels in esophageal cancer patients." (PMID 38066484, 2023). "The mechanism of the correlation between PNI and postoperative complications in patients with esophageal cancer is unclear and may be determined by the role of albumin and lymphocytes." (PMID 37386418, 2023). "It is reported that the Prognostic Nutritional Index, which is calculated using serum albumin and the peripheral blood lymphocyte count, is positively correlated with tumor-infiltrating lymphocyte counts in surgically resected esophageal cancer and squamous cell lung cancer specimens." (PMID 34895201, 2021). "Previous studies have indicated that albumin levels were not always decreased in operable esophageal cancer patients, making nutritional deficiency insufficient for risk stratification." (PMID 27528228, 2016). "Early EN started within 3 days is safe and valid for postoperative esophageal cancer patients and has advantages in reducing the use of albumin infusion and TPN, for promoting early recovery of intestinal movement, and for early recovery from systemic inflammation." (PMID 24067386, 2013). "Reduced albumin levels signify protein-energy malnutrition and impaired hepatic protein synthesis, leading to compromised wound healing, weakened immunity, and diminished tolerance to treatment, issues that are especially pronounced in esophageal cancer due to dysphagia-related nutritional decline." (PMID 41179090, 2025). "However, whether the decreased perioperative serum albumin level has the impact on esophageal cancer patients treated with neoadjuvant therapy followed by surgery is still controversial." (PMID 38066484, 2023).
esophageal cancer (continued). "A recent study reported the beneficial impact of fluoroscopy-assisted PDT combined with nanoparticle albumin-bound paclitaxel (Nab-P) in removing the tumor mass, keeping the organ intact without losing its function, and excellent treatment outcomes in locally advanced esophageal cancer." (PMID 34834358, 2021). "The NUn score, which integrates CRP, ALB, and WBC values, was initially developed to predict anastomotic leakage in esophageal cancer." (PMID 40299490, 2025). "Regarding esophageal cancer, CONUT, PNI, PG-SGA, and NRS-2002 are more commonly used, while albumin is also frequently evaluated." (PMID 37873749, 2023). "We also observed that the patients with good PS, esophageal cancer, ICI combined therapy in the first-line or second-line setting, an occurrence of irAEs, and baseline albumin level > 39.2 g/L displayed higher DCR (all p < 0.05)." (PMID 37207161, 2023). "For metastatic esophageal cancers, the most important prognostic factors were FBG, albumin and cancer staging including differentiation and invasion depth whereas BMI and REE did not significantly affect the OS." (PMID 28003023, 2016). "An investigation of nutritional status at 3, 6, and 12 months after surgery for esophageal cancer found no alterations in albumin levels but decreases in body mass index and cholinesterase at 3 months after surgery, followed by gradual recovery." (PMID 39570570, 2024). "The PNI score is calculated as “albumin level (g/L) + 0.005 × lymphocytes”; decreased PNI score correlates with poor prognosis in patients with advanced-stage cancer treated with immune checkpoint inhibitors and in patients with pancreatic, renal, and esophageal cancers." (PMID 36661734, 2023). "At present, whether there is a correlation between the changes of hemoglobin and albumin and the decrease of lymphocytes during radiotherapy for esophageal cancer has not been reported." (PMID 36959779, 2023). "Therefore, considering such aspects, in esophageal cancer surgery, it would be better to perform restrictive fluid therapy using only crystalloid or using other colloids such as albumin, rather than HES." (PMID 30717728, 2019). "Similarly, a previous study for 4 weeks of ONS on esophageal cancer patients undergoing chemotherapy or radiation therapy reported no significant changes in the total serum protein, serum albumin, total cholesterol and hemoglobin." (PMID 31121926, 2019). "Moreover, survival was found to be significantly worse in patients with advanced esophageal cancer treated by chemotherapy and CRT if they had a low Prognostic Nutritional Index (PNI; also known as the Onodera Index), which is calculated from the serum albumin level and total lymphocyte count." (PMID 40155587, 2025). "Besides, albumin levels were not always decreased in esophageal cancer patients." (PMID 27517497, 2016).
acute pancreatitis (81 papers, 2015 to 2026). An acute inflammatory process that leads to necrosis of the pancreatic parenchyma. "On the other hand, serum albumin, a marker of nutritional and inflammatory status, is known to decrease in critically ill patients and has been linked to worse clinical outcomes in acute pancreatitis." (PMID 40291314, 2025). "In this study, multivariate logistic proportional regression analysis and restricted cubic spline regression were used to evaluate the association between serum urea nitrogen/albumin ratio and in-hospital mortality in patients with severe acute pancreatitis." (PMID 40971376, 2025). "A high serum urea nitrogen to albumin ratio was significantly associated with in-hospital mortality in patients with severe acute pancreatitis." (PMID 40971376, 2025). "This meta-analysis demonstrated that reduced serum albumin levels at hospital admission are significantly associated with a higher risk of AKI among patients with acute pancreatitis." (PMID 41523521, 2025). "Several studies have consistently shown that lower albumin is linked to the severity and high mortality of acute pancreatitis." (PMID 41171733, 2025). "A study of a larger number of survivor and nonsurvivor dogs would be necessary to further evaluate the association between MCAI and serum albumin concentration in dogs with acute pancreatitis." (PMID 34250650, 2021). "The independent risk factors positively associated with ARC were weight, gestational age, albumin level, infection, hypertriglyceridemia and acute pancreatitis." (PMID 34177564, 2021). "One study did not favor the laboratory markers on admission had a prognostic value, rather NLR, PLR, and CRP/albumin ratio at 48 hours of hospital stay were significantly associated with acute pancreatitis complications." (PMID 34513375, 2021). "High levels of NLR, PLR, RDW, glucose, CRP, urea, potassium, low albumin and hematocrit values ​​at the first admission in the Emergency Service seem to be associated with increased 1-year mortality in acute pancreatitis." (PMID 33489590, 2020). "High levels of NLR, PLR, RDW, glucose, CRP, urea, potassium, low albumin and hematocrit values at the first admission in the Emergency Department seem to be associated with increased 1-year mortality in acute pancreatitis." (PMID 33489590, 2020). "The rapid rise in the amount of ascites output and the levels of amylase and albumin in the blood and ascites are characteristic, and are usually diagnostic criteria of acute pancreatitis." (PMID 28115014, 2017). "An increase in serum albumin level was associated with a statistically significant reduction in the odds of persistent organ failure and mortality of acute pancreatitis after adjusting for potential confounders." (PMID 29147647, 2017). "A low serum albumin is independently associated with an increased risk of developing of persistent organ failure and death in acute pancreatitis." (PMID 29147647, 2017). "Several mechanisms may explain why low serum albumin levels predispose patients with acute pancreatitis to kidney injury." (PMID 41523521, 2025). "Similarly, in dogs, elevated CRP/ALB ratios have been associated with increased mortality risk in acute pancreatitis." (PMID 40218453, 2025). "Accordingly, a study found that patients with acute pancreatitis and serum albumin levels less than 25 g/L anytime during hospitalization had a 16.8-fold higher risk of death and 48.8-fold higher risk of severe acute pancreatitis than patients with normal albumin levels." (PMID 39980616, 2024). "Furthermore, to the best of our knowledge, no study has performed a complete overview of the association between serum albumin levels at admission and outcomes in acute pancreatitis up until now." (PMID 29147647, 2017). "Despite these limitations, the consistency and robustness of the pooled findings strongly support the association between low serum albumin and the development of AKI in acute pancreatitis." (PMID 41523521, 2025).